HNRNPA1 (heterogeneous nuclear ribonucleoprotein A1)
Diseases named in the same sentence as HNRNPA1 in open-access papers (continued):
Sharing a sentence is not in itself a finding about the gene and the disease.
prostate carcinoma (continued). "Recent studies indicate that fusing factors such as hnRNPA1 promote the production of AR-V7 and thus contribute to the resistance of enzalutamide in cells of prostate cancer." (PMID 33807174, 2021). "In breast, colorectal and prostate cancer cells, PRMT4/5/7 are upregulated and associated with high levels of hnRNPA1 arginine methylation and aberrant alternative splicing." (PMID 33782401, 2021). "There is growing evidence that hnRNPA1 also plays an important role in prostate cancer biology and therapy." (PMID 32417965, 2020). "Here, we took advantage of our large set of more than 17,000 cancer specimens available in a tissue microarray (TMA) format to study hnRNPA1 protein expression in prostate cancer and to determine its clinical significance." (PMID 32417965, 2020). "To study the impact of hnRNPA1 expression in prostate cancer, we analyzed a tissue microarray containing 17,747 clinical prostate cancer specimens by immunohistochemistry." (PMID 32417965, 2020). "This is particularly important, since the levels of hnRNPA1 increase in prostate cancer, and hnRNPA1 expression has been observed as an early marker for tumour development in several cancers." (PMID 28382513, 2017). "Lin28 expression increases in prostate cancer and regulates the expression of Let7 family microRNAs that operate upstream of Myc and a number of splicing factors including hnRNPA1 that in turn control ARv7 production." (PMID 28382513, 2017). "Heterogeneous nuclear ribonucleoprotein A1 (hnRNPA1) was identified as a target of quercetin in prostate cancer cell line, PC352." (PMID 27068577, 2016). "Our study revealed that circSPIRE1, regulated by hnRNPA1’s SDMA-mediated post-translational modifications, undergoes rolling circle translation to encode rtSPIRE1, which promotes prostate cancer progression by stabilizing LRP5 and activating the PI3K/AKT signaling pathway." (PMID 40713830, 2025). "Patients with low ZMYND11/high HNRNPA1 expression exhibited significantly shorter biochemical recurrence- or metastasis-free survival compared to those with high ZMYND11/low HNRNPA1 expression, indicating a synergistic prognostic effect of both genes on prostate cancer severity." (PMID 39341825, 2024). "Given the correlation between ZMYND11 downregulation or HNRNPA1 upregulation and adverse outcomes in prostate cancer patients, we then examined whether these observations have relevant clinical implications." (PMID 39341825, 2024). "In breast, colorectal, and prostate cancers, PRMT4, 5, and 7 were upregulated and associated with high levels of arginine methylation on their-regulated methylome, such as hnRNPA1, and aberrant gene alternative splicing, thereby potentially driving cancer cell growth." (PMID 33782401, 2021). "hnRNPA1 plays a crucial role in regulating cell proliferation, invasiveness, metabolism, and immortalization in multiple tumors such as hepatocellular carcinoma, prostate cancer, and oral squamous cell cancer." (PMID 33573689, 2021). "The results of our study demonstrate that upregulation of hnRNPA1 is associated with adverse tumor features and poor prognosis in the subset of prostate cancers lacking TMPRSS2:ERG fusions." (PMID 32417965, 2020). "Since Quercetin suppresses hnRNPA1 levels in prostate cancer cells, we evaluated whether hnRNPA1 mediates the anti-tumor effects of Quercetin in thyroid and pancreatic cancer cells." (PMID 31480735, 2019). "Furthermore, it was shown that the downregulation of hnRNPA1 by quercetin, a flavonoid abundantly present in plants, concomitantly decreases the expression of AR-V7, resensitizing enzalutamide-resistant prostate cancer cells to enzalutamide treatment in mouse xenografts." (PMID 32106418, 2020). "However, another study suggested that hnRNPA1 suppresses AR-V7 expression in prostate cancer cells." (PMID 32106418, 2020). "It interacts directly with HNRNPA1 RBD, lowering downstream AR-V7 levels, thus inhibiting castration-resistant prostate cancer." (PMID 39062595, 2024).
prostate carcinoma (continued). "We discovered that ZMYND11 can physically interact with HNRNPA1 via its MYND domain, and this interaction is crucial for ZMYND11 to counteract HNRNPA1-induced aggressive phenotypes in prostate cancer cells." (PMID 39341825, 2024). "Altogether, our data elucidate the oncogenic and clinical impacts of HNRNPA1 on prostate cancer progression and demonstrate that ZMYND11 attenuates the oncogenic capabilities of HNRNPA1 through binding mediated by the MYND domain of ZMYND11." (PMID 39341825, 2024). "The critical roles of PRMT4, PRMT5, PRMT7, and hnRNPA1 in cell growth were also demonstrated in HCT 116 cells, a colon cancer cell line, and LNCaP, a prostate cancer cell line." (PMID 33782401, 2021). "RASSF2, which is a tumor-suppressor in the prostate cancer mouse model, might be coregulated by FXR1, FXR2, HNRNPA1, PTBP1, G3BP1, HNRNPF, and SRSF7." (PMID 32316190, 2020). "NFKB2, which is involved in aberrant activation of androgen receptor in prostate cancer cells, might be coregulated by FXR2 and HNRNPA1 proteins based on our motif enrichment analysis." (PMID 32316190, 2020). "hnRNPA1 measurement, either alone or in combination, might provide prognostic information in ERG-negative prostate cancer." (PMID 32417965, 2020). "Since hnRNPA1 is a MNK effector, and is inhibited by Quercetin in prostate cancer cells, we evaluated whether hnRNPA1 knockdown also enhances the anti-tumor effects of BET inhibitors." (PMID 31480735, 2019). "However, the mechanisms by which hnRNPA1, through specific post-translational modifications, mediates circRNA IRES activity and drives prostate cancer progression remain unknown." (PMID 40713830, 2025). "Additionally, we evaluated HNRNPA1 protein levels in a collection of prostate cancer patient samples compared to surrounding non-tumor tissues using IHC, finding elevated HNRNPA1 expression in tumor specimens." (PMID 39341825, 2024). "However, data on the prevalence and clinical significance of hnRNPA1 protein expression in prostate cancer are still lacking in the literature." (PMID 32417965, 2020). "Notably, HNRNPA1 expression was predictive of disease recurrence in prostate cancer patients with a Gleason score of 7 but not in those with Gleason scores ≤6 or ≥8, suggesting a prognostic potential of HNRNPA1 in patient stratification." (PMID 39341825, 2024).
colorectal cancer (19 papers, 2016 to 2025). A primary or metastatic malignant neoplasm that affects the colon or rectum. "The comparative expression patterns and diagnostic efficiencies of HNRNPA1 and SR splicing factors were discovered in gastric and colorectal cancers." (PMID 33842552, 2021). "miR-27b regulation by RNPs has only been reported for HnRNPa1 in colorectal cancer and HnRNPa2b1 in preeclampsia." (PMID 38804364, 2024). "The SNHG6/hnRNPA1 complex contributes to colorectal cancer metastasis by enhancing aerobic glycolysis." (PMID 33050646, 2020). "Upregulated expression and aberrant cytoplasmic localization of HNRNPA1, as determined by immunohistochemical staining, were noted in colorectal cancer (CRC)." (PMID 27282379, 2016). "Here, we found that kaempferol could inhibit the expression of PKM2, the key enzyme of glycolysis, and the three splicing factors of the PKM gene, PTBP1, hnRNPA1 and hnRNPA2, thus reversing the resistance of colorectal cancer cells to 5-Fu." (PMID 35408903, 2022). "In colorectal cancers, it is reported that lncRNA SNHG6 directly combines with the hnRNPA1 complex, which includes hnRNPA2B1 and PTB, and then increases the proportion of PKM2/PKM1." (PMID 33050646, 2020). "In colorectal cancer cells, KMP overcame 5-FU resistance by regulating the microRNA-326–heterogeneous nuclear ribonucleoprotein A1/A2/polypyrimidine tract-binding protein 1–pyruvate kinase M2 (miR-326–hnRNPA1/A2/PTBP1–PKM2) axis." (PMID 38339336, 2024). "Moreover, lncRNA SNHG6 binds to hnRNPA1 and subsequently facilitates hnRNPA1-mediated splicing of PKM, resulting in an increased PKM2/PKM1 ratio, aerobic glycolysis and carcinogenic progression in colorectal cancer." (PMID 40612109, 2025).
lung carcinoma (16 papers, 2014 to 2025). "Overexpression of Eef1b2 and Hnrnpa1 has been previously linked with cancer progression and poor prognosis in breast and lung cancer." (PMID 39165691, 2024). "In-depth study of the AS regulation mechanism and biological effects of hnRNPA1 can provide an important theoretical basis and new layer for lung cancer research." (PMID 35814393, 2022). "HNRNPA1 has been reported overexpressed in many malignancies such as lung cancer, myeloma, leukemia, and Burkitt lymphoma." (PMID 36147313, 2022). "Analogously, the role of hnRNPA1 loading batched miRNAs/lncRNAs into EVs was revealed in lung cancer, bladder cancer (BCa) and advanced head and neck cancer (HNC) as well." (PMID 35879279, 2022). "Increased expression of HNRNPA1 is also reported to be involved in drug resistance in pancreatic and lung cancer." (PMID 36293493, 2022). "In lung cancer, knockdown of HNRNPA1 suppressed the viability and growth as well as induced cell cycle arrest of lung cancer cells." (PMID 32915499, 2020). "In summary, we find that HOTAIR can regulate HNRNPA1 expression through a ceRNA mechanism by sequester miR-149-5p, which post-transcriptionally targets HNRNPA1, thus promoting lung cancer progression." (PMID 33102210, 2020). "To further explore whether hnRNPA1 affects lung cancer metastasis and its potential molecular mechanism, we firstly designed an independent shRNA targeted against hnRNPA1, and verified the efficiency in the NSCLC cell lines of A549 and H1299." (PMID 35814393, 2022). "HnRNPA1 could augment the proliferation activity of lung cancer cells by directly binding to the 3ʹUTR of vaccinia related kinase 1 (VRK1) mRNA, expediting its translation and then increasing cyclin D1 expression." (PMID 35879279, 2022). "hnRNPA1 has been reported to be involved in the regulation of tumor metastasis, while its specific role in tumor metastasis seems to be controversial and its molecular mechanism in lung cancer metastasis remains to be further elucidated." (PMID 35814393, 2022). "In our study, we find that HNRNPA1 is a downstream target gene of miR-149-5p, and miR-149-5p could inhibit the protein expression of HNRNPA1 in a lung cancer cell line." (PMID 33102210, 2020). "Moreover, hnRNPA1 expression showed significant heterogeneity in lung cancer tissues, which may contain new research directions and potential therapeutic targets." (PMID 35814393, 2022). "Results of the dual-luciferase reporter assay show that, miR-149-5p could bind to 3′UTR of mRNA of HNRNPA1, thus inhibiting the protein expression of HNRNPA1, which provided a biological plausible evidence for tumor suppressor role of miR-149-5p in lung cancer." (PMID 33102210, 2020). "In lung cancer, ESCO2 acetylates hnRNPA1, maintaining it in the nucleus and ultimately enhancing aerobic glycolysis by increasing PKM2 and decreasing PKM1 expression." (PMID 40657363, 2025). "More importantly, our data showed that hnRNPA1 depletion can inhibit exclusion of LAS1L exon 8 to produce the LAS1L-L protein isoform, thus promoting EMT transition and metastasis capacity of lung cancer cells in vivo." (PMID 35814393, 2022). "Our results indicate that hnRNPA1 can affect the metastasis of lung cancer cells by modulating the AS of LAS1L exon 9, highlighting the potential significance of hnRNPA1 in lung cancer metastasis." (PMID 35814393, 2022). "Further Transwell assays indicated that the expression ratio of LAS1L-L/LAS1L-S regulated by hnRNPA1 can further promote the migration, invasion and EMT transition in lung cancer cells." (PMID 35814393, 2022). "In summary, our findings reveal the tumorigenic effects of hnRNPA1 and its downstream LAS1L- isoform in lung cancer cell metastasis and EMT transition." (PMID 35814393, 2022). "In this study, we confirmed that knockdown of the hnRNPA1 led to enhanced migration, invasion and EMT transition in lung cancer cells." (PMID 35814393, 2022).
lung carcinoma (continued). "In the present study, we investigate the effect of miR-149-5p, HNRNPA1, and HOTAIR on lung cancer cells." (PMID 33102210, 2020). "As report goes, hnRNPA1 was the most frequently (76%) overexpressed hnRNPA/B family protein in non-small cell lung cancer (NSCLC) and was negatively correlated with the overall survival of patients with lung cancer." (PMID 35879279, 2022).
hepatocellular carcinoma (15 papers, 2019 to 2026). A malignant tumor that arises from hepatocytes. "Furthermore, HNRNPA1 knockdown significantly inhibited the overexpression of CD44v6 and caused an apparent decrease in the invasive capacity of tumor cells in hepatocellular carcinoma, while HNRNPA1 upregulation, caused by miR-490, promoted cell proliferation and migration." (PMID 35022405, 2022). "In hepatocellular carcinoma, SIRT1 and SIRT6 cause de-acetylation at K3, K52, K87, and K350 lysine residues in hnRNPA1, hindering the splicing transition from PKM to PKM2 mRNA." (PMID 38785973, 2024). "LncRNA ANCR promoted the metastasis of hepatocellular carcinoma by upregulating hnRNPA1 and inhibiting hnRNPA1 degradation." (PMID 37897508, 2024). "It has been reported that TKP significantly reduces β-catenin expression in a dose-dependent manner and inhibits the β-catenin/c-Myc/hnRNPA1 signaling cascade, thereby inhibiting glycolysis and cell proliferation of hepatocellular carcinoma cells." (PMID 38785973, 2024). "Recently, hnRNPA1 is indicated as the oncogene in the pathogenesis of hepatocellular cancer and colon cancer, and hnRNPA1 promotes cell proliferation by regulating translation of diverse antiapoptotic proteins." (PMID 35875075, 2022). "For example, HNRNPA1 is highly expressed in hepatocellular carcinoma and lung adenocarcinoma to promote tumor progression." (PMID 31257225, 2019). "Most evidence shows that miRNAs inhibit glycolysis in tumor cells by targeting the alternative splicing of PKM, and miR-374b affects the splicing of PKM1/PKM2 by changing the expression of hnRNPA1, which makes sorafenib-resistant hepatocellular carcinoma cells sensitive to sorafenib therapy." (PMID 35408903, 2022). "In hepatocellular carcinoma (HCC), HNRNPA1 contributes to development by regulating cell cycle, mitochondrial dynamics, and necrotic apoptosis pathways." (PMID 39717265, 2024). "In hepatocellular carcinoma, ZFP91 promotes hnRNPA1 ubiquitination and inhibits PKM2 splicing, while SIRT1/6 inhibitors regulate hnRNPA1 acetylation to control PKM2 expression." (PMID 40842995, 2025).
colon cancer (13 papers, 2006 to 2024). "The expression of KITENIN was associated with the expression of hnRNPI, hnRNPA1, and hnRNPA2 in colon cancer using the GEPIA analysis tool." (PMID 37553596, 2023). "PRMT4, 5, and 7 and hnRNPA1 arginine methylation are found to be overexpressed in multiple types of human cancers (including breast, prostate, and colon cancer) and associated with altered cancer-relevant alternative splicing events." (PMID 33782401, 2021). "For instances, hsa_circ_0004085 is upregulated in colon cancer and fusobacterium nucleatum infection can promote hsa_circ_0004085 formation by hnRNP L and packaged hsa_circ_0004085 into exosomes by hnRNPA1." (PMID 38737906, 2024). "MiR-339-5p has also been reported to inhibit glycolysis and colon cancer growth by reducing PKM2 expression through hnRNPA1 and PTBP1." (PMID 34782005, 2021). "Interestingly, knockdown of HNRNPA1 was reported to positively regulate transcription of TRA2B in colon cancer cells." (PMID 32631453, 2020). "HnRNPA1 mRNA levels were positively correlated with the expression levels of TRA2β1, whereas expression levels of hnRNPA1 showed weak correlation with those of TRA2β4 in the colon cancers." (PMID 31311954, 2019). "Although this is the limited survey, these results suggest that hnRNPA1 and hnRNPU may contribute Tra2β overexpression in colon cancer cells." (PMID 31311954, 2019). "Our results suggest that hnRNPA1 may modulate TRA2B transcription through its regulation of G4 formation in its promoter in colon cancer cells." (PMID 31311954, 2019). "The HOXB-AS3 peptide can competitively bind to the arginine residue in the hnRNPA1 RGG motif and inhibit the binding of hnRNPA1 to PKM, which further down-regulates the level of PKM2 and inhibits the metabolism reprogramming process of colon cancer cells." (PMID 38785973, 2024). "Using Tissue Scan RT Colon Cancer Disease Panels III HCRT103 (OriGene, MD, USA), mRNA levels of hnRNPA1, hnRNPU, or TRA2β1 and TRA2β4 levels in 24 patients with colon cancers were measured by RT-qPCR." (PMID 31311954, 2019). "The expression levels of antagonistic splicing factors, such as hnRNPA1 and SF2/ASF, have been shown to affect splice site selection, and colon cancer progression." (PMID 16995940, 2006). "In addition, kaempferol promotes miR-339-5p expression, which directly targets hnRNPA1 and PTBP1, reducing PKM2 expression and inhibiting glycolysis in colon cancer." (PMID 38785973, 2024).
multiple sclerosis (9 papers, 2016 to 2025). A progressive autoimmune disorder affecting the central nervous system resulting in demyelination. "Altered patterns of splicing are associated with mislocalized HNRNPA1 protein in multiple sclerosis." (PMID 40750357, 2025). "hnRNPA1 is also involved in alternative splicing and altered splicing was recently found in a mouse model of hnRNPA1 mislocalization-associated multiple sclerosis." (PMID 39386562, 2024). "For example, studies have demonstrated that Hnrnpa1 dysfunction contributes to neurodegeneration in multiple sclerosis experimental models, and mutations in ATP13A2 have been established as the causative factor for Kufor-Rakeb syndrome, a rare form of juvenile-onset Parkinsonism." (PMID 39858933, 2025). "In addition, single nucleotide variants in hnRNPA1 have also been demonstrated to be implicated in the pathogenesis of multiple sclerosis." (PMID 36314424, 2022). "Evidence indicates that dysfunctional heterogeneous ribonucleoprotein A1 (hnRNPA1; A1) contributes to the pathogenesis of neurodegeneration in multiple sclerosis." (PMID 33809384, 2021). "Multiple sclerosis patients develop antibodies to the RNA-binding protein, heterogeneous nuclear ribonucleoprotein A1 (hnRNP A1), which is enriched in neurons." (PMID 27391474, 2016). "Antibodies, including antibodies to the RNA binding protein heterogeneous nuclear ribonucleoprotein A1, have been shown to contribute to the pathogenesis of multiple sclerosis, thus it is important to assess their biological activity using animal models of disease." (PMID 30768649, 2019).